CCR10 (C-C motif chemokine receptor 10)
Description:
Receptor for chemokines SCYA27 and SCYA28. Subsequently transduces a signal by increasing the intracellular calcium ions level and stimulates chemotaxis in a pre-B cell line.
Synonyms: GPR2
Tractability: Small molecule: a high-quality ligand is known; it belongs to a druggable protein family. Antibody: its Gene Ontology location is reachable by antibodies, with high confidence; UniProt places it where antibodies can reach, with medium confidence; UniProt predicts a signal peptide or a membrane-spanning region. PROTAC: a small molecule that binds it is known.
Target class: Chemokine receptor; Peptide receptor (family A GPCR); Family A G protein-coupled receptor; CC chemokine receptor; Membrane receptor
Chemical probes: BI-6901 (high quality)
Gene: Protein-coding gene on chromosome 17 (42,678,889 to 42,683,917, reverse strand). Ensembl gene ENSG00000184451.
Subcellular location: Cell membrane
Subcellular location (Human Protein Atlas): Endoplasmic reticulum
Pathways (Reactome):
Signal Transduction: Chemokine receptors bind chemokines; G alpha (i) signalling events
Gene Ontology:
Molecular function: protein binding; C-C chemokine binding; C-C chemokine receptor activity; G protein-coupled receptor activity; chemokine receptor activity
Biological process: calcium-mediated signaling; cell chemotaxis; G protein-coupled receptor signaling pathway; immune response; positive regulation of cytosolic calcium ion concentration; chemokine-mediated signaling pathway; chemotaxis
Cellular component: cell surface; external side of plasma membrane; plasma membrane; membrane
Genetic constraint (gnomAD): Loss-of-function variants: 11 observed, 10.84 expected, observed/expected ratio (o/e) 1.01, 90% interval 0.64 to 1.65. The upper end of that interval is the gene's LOEUF score, 1.65, which puts it in group 6 of 6, group 1 being the genes least tolerant of losing a copy. Missense variants: 427 observed, 443.55 expected, observed/expected ratio (o/e) 0.96, 90% interval 0.89 to 1.04. Synonymous variants: 224 observed, 217.52 expected, observed/expected ratio (o/e) 1.03, 90% interval 0.92 to 1.15.
Homologues: Orthologues: chimpanzee CCR10 (100% identical), macaque CCR10 (98% identical), pig CCR10 (93% identical), rabbit CCR10 (93% identical), dog CCR10 (92% identical), mouse Ccr10 (88% identical), rat Ccr10 (88% identical), guinea pig CCR10 (84% identical), zebrafish ccr10 (30% identical). Paralogues in human: CCR7 (37% identical), CXCR3 (35% identical), CCR9 (32% identical), ACKR4 (32% identical), ACKR2 (31% identical), CCR6 (30% identical), CXCR5 (30% identical), CXCR2 (30% identical), CCR5 (28% identical), CCR1 (28% identical), CCR3 (28% identical), CXCR1 (28% identical), and 11 more.
Diseases named in the same sentence as CCR10 in open-access papers:
CCR10 is named in the same sentence as 90 diseases in open-access papers, as found by Europe PMC text mining. Sharing a sentence is not in itself a finding about the gene and the disease. The quoted sentences say what the papers report.
melanoma (28 papers, 2010 to 2025). A malignant, usually aggressive tumor composed of atypical, neoplastic melanocytes. "Expression of CXCR4, CCR7 and CCR10 on the surface of melanoma cells is associated with a poor prognosis." (PMID 35158973, 2022). "Compared to controls, Ccr10 and Cxcl12/Cxcr4 levels were decreased in B16 melanoma tumors from Cbx3/HP1γ-deficient mice." (PMID 34721405, 2021). "Altogether, CCR10 overexpression on melanoma cells is associated with the possible presence of regional lymph node metastases accompanied by an immune negative climate." (PMID 30420855, 2018). "Consistent with our present findings, CCR10 activation has been associated with promoting the development of malignant melanoma and glioma through stimulating cell proliferation." (PMID 29445190, 2018). "Interaction of chemokine receptor 10 (CCR10) with its ligand causes T cell homing and metastasis in melanoma; higher expression of CCR10 was correlated with lower survival of glioblastoma patients." (PMID 28174608, 2017). "CCR10 has been implicated in directly providing melanoma with resistance to cytotoxic immune cells." (PMID 34830780, 2021). "In melanoma patients, high CCR10 expression is associated with a short survival." (PMID 34806028, 2021). "Moreover, the receptors CXCR3, CXCR4, CCR7 and CCR10 have been implicated in the process of metastasis in melanoma, based on studies with animals." (PMID 24559071, 2014). "In melanoma CCR10 is up-regulated by TNF-α, IL-1β, and growth factors, with higher expression in node-positive cases." (PMID 41050670, 2025). "CCR10 expression in melanoma cells was correlated with significantly lower survival time and time to progression, as well as a higher chance of cerebral metastasis." (PMID 39982274, 2025). "CCL27, a chemokine expressed in the epidermis by normal keratinocytes, seems to interact with the chemokine receptor CCR10, which is expressed in melanoma cells." (PMID 37833981, 2023). "The CCR10/CCL27 axis plays a significant role in tumour development, which is illustrated by the link between CCR10 overexpression in primary melanoma cells and increased regional lymph node metastasis." (PMID 37170733, 2023). "Another crucial factor in melanoma metastasis to the skin is represented by the interactions between chemokines C-C motif chemokine receptor 10 (CCR10) and C-C motif chemokine ligand 27 (CCL27)." (PMID 37833981, 2023). "CCR10 is also expressed by melanocytes and CCR10‐transduced melanoma cell lines possess superior metastatic potential." (PMID 37144705, 2023). "In mice, the overexpression of CCR7 or CCR10 in B16 melanoma cells was shown to increase regional lymph node metastases, which was blocked by neutralizing its ligand, CCL21, using a specific antibody." (PMID 35158973, 2022). "This suggests that despite the local accumulation of CCL27, CCR10-expressing T cells are unable to infiltrate CCL27-expressing melanoma lesions and these T cells are therefore restricted to circulate in the periphery." (PMID 30420855, 2018). "Using a preclinical model of melanoma, overexpression of CCR10 in B16 tumor cells protected them from the host immune responses leading to an increase in tumor size and increased regional lymph node metastases." (PMID 30420855, 2018). "We first visualised the distribution of CCR10 in the human melanoma cell line UKRV-Mel-4 known to express CCR1017 using confocal immunofluorescence microscopy." (PMID 26941067, 2016). "Recently, immunohistochemical expression of CXCR4, CCR7 and CCR10 and their ligands has been described in tumor cells from primary and metastatic melanomas." (PMID 24559071, 2014). "We have evaluated, using flow cytometry, the expression of the chemokine receptors CXCR4, CXCR3, CXCR7, CCR7 and CCR10, at cell surface and intracellular levels, for thirteen human melanoma cell lines." (PMID 24559071, 2014). "B16 melanoma cell transduction of CCR10 significantly increases the development of lymph node metastasis in mice after inoculation in the skin." (PMID 25149529, 2014).
melanoma (continued). "Melanoma cell transduction of CCR10 significantly increases the development of lymph node metastasis in mice after inoculation in the skin." (PMID 25149529, 2014). "Given the role of CCR10-CCL27 in leukocyte migration to the skin, it is likely that CCR10 expression in melanoma induces metastasis to the skin." (PMID 24259307, 2013). "The mechanisms by which chemokine receptors on tumor cells facilitate LN metastasis are illustrated by studies on the roles of CCR7 and CCR10 in experimental metastasis of B16 murine melanoma cells." (PMID 24212647, 2011). "Chemokines, specifically interactions between CCR10 and CCL27, have been implicated in melanoma metastasis to the skin." (PMID 24212610, 2010). "CCL27 is a chemokine expressed constitutively in the epidermis by normal keratinocytes, and is thought to interact specifically with the chemokine receptor CCR10, which is expressed on melanoma cells." (PMID 24212610, 2010). "CCR10 influences the immune system, allowing melanoma cells to evade immunosurveillance." (PMID 39982274, 2025). "In addition to promoting melanoma metastasis to the lymph nodes, the CCR10/CCL27 axis is also involved in mediating tumour proliferation, invasion, and immune escape, thus directly correlating with cancer progression." (PMID 37170733, 2023). "In addition, overexpression of CCR10 in the B16 melanoma mouse model resulted in increased tumor size and lymph node metastases." (PMID 34806028, 2021). "Similarly, the downregulation of CCR10 tumour cells contributed to the inhibition of cancer stem cell growth and metastases in both melanoma and squamous cell carcinoma." (PMID 31747966, 2019). "Similarly, previous work has shown that activation of CCR10 contributes to carcinogenesis and invasive progression in melanoma and glioma cells in vivo." (PMID 29445190, 2018). "CCR10 is expressed on melanoma cells in primary tumor lesions." (PMID 30420855, 2018). "Moreover, previous studies in malignant melanoma and glioma suggest that CCR10 promotes cellular proliferation through PI3K/Akt pathway activation." (PMID 29445190, 2018). "Our next step is to examine in tumor-bearing animals whether these CCR10+-activated killer cells may migrate into the sites of colorectal cancers or melanomas after pretreatment with GA, MMF, or DMF." (PMID 27807435, 2016). "Gene expression studies at the mRNA level have shown that human melanoma cell lines express CXCR4 and also receptors CCR10 and CCR7 which could be implicated in the frequent metastasis of melanoma to skin and lymph nodes, respectively." (PMID 24559071, 2014). "In this study we have analyzed, using flow cytometry, the systems formed by the chemokine receptors CXCR3, CXCR4, CXCR7, CCR7 and CCR10 and their ligands in thirteen human melanoma cell lines (five established from primary tumors and eight established from metastasis from different tissues)." (PMID 24559071, 2014). "Their results suggest that in human melanomas CCR10 and CCL27 may act on the ability of neoplastic cells to grow, invade tissue, disseminate to lymph nodes and to escape the host immune response." (PMID 24559071, 2014). "The chemokine receptor CCR10 is expressed on melanoma cells." (PMID 24259307, 2013). "Thus, CCL27/CCR10 contributes to the growth of melanoma cells by the activation of PI3K/Akt pathway and by evading the host anti-tumor response." (PMID 24259307, 2013). "However, another study suggests that CCR10 expression in melanoma promotes metastasis to the lymph nodes in addition to enhancing invasion, growth, and immune escape of tumor cells." (PMID 24259307, 2013). "Studies show that malignant melanoma expresses high levels of CCR10 in addition to CXCR4 and CCR7." (PMID 24259307, 2013). "However, another study hypothesised that T cells expressing CCR10 are unable to infiltrate melanoma lesions expressing CCL27." (PMID 37170733, 2023).
melanoma (continued). "Thus, CCR10 and CXCL12/CXCR4 may regulate homing of CD4+ Tregs to B16 melanoma tumors while invasion of NBL tumors by CD4+ Tregs is likely governed by CCL28/CCR10 and CXCL12." (PMID 34721405, 2021). "Because heterologous overexpression of GPCRs in cell lines might fail to reflect the GPCR activation pattern seen in the native cellular environment, we analysed CCR10 localisation in the malignant melanoma UKRV-Mel-4 cell line which expresses a substantial amount of endogenous CCR1017." (PMID 26941067, 2016). "In melanoma S100A10 binds the CCR10 cytosolic tail, linking it to annexin A2 and regulating CCR10 surface expression; S100A10 knockdown increases CCR10 levels and disrupts annexin A2 association, underscoring its role in CCR10 localization and stability." (PMID 41050670, 2025). "Certain chemokines, including CCR10 and CXCR3, have been demonstrated to play a pivotal role in the proliferation and metastasis of melanoma cells." (PMID 39079132, 2024). "The major chemokine/chemokine receptor interactions occurring in melanoma development and progression include the CXCR4/CXCR7/CXCL12, CXCR3/CXCL9,10,11, CXCR1,2/CXCL8, CCR2/CCL2, CCR4/CCL17,22, CCR5/CCL5, CCR7/CCL21 and CCR10/CCL27 axes." (PMID 37170733, 2023). "When CCL27 was added, signalling through CCR10 led to activation of the Akt and PI3K pathways, enabling melanoma cells to resist Fas-mediated apoptosis, a key mechanism in tumour cell clearance." (PMID 34830780, 2021). "For example, malignant melanomas express higher levels of CXCL1, CXCL2, and CXCL8 and receptors CXCR1, CXCR4, CCR10, and CCR7 compared with benign naevi." (PMID 34830780, 2021). "Some chemokines, such as CCR10 and CXCR3, have been shown to play an important role in the proliferation and metastasis of melanoma cells." (PMID 32310824, 2020). "In a screen of several melanoma cell lines it was detected that the expression of chemokine receptors CCR7, CCR10, CXCR1, CXCR2 and CXCR4 can dramatically increase the rate of metastases and define their preferential site." (PMID 26197340, 2015). "Genes, such as IFIT2, CCR10, and TMEM97, are important for the invasion of various cancer cells, such as oral cancer, melanoma, and glioma, but these genes may be responsible for the invasion of BRCA cells." (PMID 31311202, 2019). "The machinery driving the colonization by melanoma cells of metastatic sites, including the bone, has been poorly investigated although previous studies correlated the CXCR3, CXCR4, CCR7 and CCR10 expression with the enhanced propensity to migrate to lymph nodes, lung and skin." (PMID 31324252, 2019). "Interactions between CCR10 and CCL27 are thought to mediate metastasis to the skin, supported by the observation that neutralizing antibodies to CCL27 can block formation of B16 melanoma in mouse ear skin." (PMID 24212610, 2010). "Hence, CCR10 engagement by locally produced CCL27 facilitates melanoma progression, most likely through activation of PI3K/Akt, which may allow melanoma cells to escape host immune antitumor killing mechanisms." (PMID 24212647, 2011).
psoriasis (13 papers, 2017 to 2025). An autoimmune condition characterized by red, well-delineated plaques with silvery scales that are usually on the extensor surfaces and scalp. "Among them, observational studies have shown that restoration of the CTACK/CCR10 immunoregulatory impairments caused by psoriasis suppresses skin T-cell hyperactivation, thereby reducing the inflammatory response associated with psoriasis." (PMID 38173728, 2023). "Compared with healthy controls, psoriasis patients with active disease had significantly higher proportion of peripheral cutaneous lymphocyte-associated antigen (CLA) + T cells expressing C–C motif chemokine receptor 10 (CCR10) and CD103 and T cells with both Th1/Tc1 and Th17/Tc17 phenotypes." (PMID 34035862, 2021). "Interestingly, CTACK and its receptor CCR10 have been shown to be upregulated in melanoma tumors and linked to inflammatory skin disorders such as psoriasis, atopy, and allergic-contact dermatitis, indicating that it may be a critical mediator of T cell-mediated skin inflammatory disorders." (PMID 39516257, 2024). "CCR10 is expressed in the skin of most patients with psoriasis and atopic or allergic contact dermatitis and plays a key role in T-cell-mediated skin inflammation." (PMID 33362847, 2020). "Moreover, ligands for CCR4—CCL17 and CCL22, and CCR10—CCL27 have been associated with AD, psoriasis, cutaneous lymphomas, and systemic sclerosis." (PMID 37371632, 2023). "Moreover, in the lesions of patients with psoriasis, CCR10+ cells are more abundant than compared in healthy individuals, facilitating T cell-mediated inflammation via CCL27-CCR10 interaction." (PMID 36700220, 2022). "Collectively, these studies highlight that targeting CCR6 and/or CCR10 to inhibit the infiltration of ILCs into the skin could be a tremendously promising therapeutic alternative in psoriasis." (PMID 34831296, 2021). "Notably, psoriasis arthritis may be distinguished from skin‐confined psoriasis by the presence of CLA+CCR4+CCR10+ T cells in peripheral blood, suggesting migration of pathogenic T‐cell clones across tissue compartments." (PMID 37144705, 2023). "A plausible model is dynamic, context-dependent control: Th2-skewed AD upregulates CCR10/CCL27, whereas psoriasis (Th1/Th17/Th22) shifts to other chemotactic cues; notably, CCR10 marks Th22 enriched in psoriasis." (PMID 41050670, 2025). "CCR10/CCL27–CCL28 help maintain homeostasis yet can drive pathology: inflammatory dermatoses (atopic dermatitis, psoriasis, allergic contact dermatitis) show abundant CCR10 T cells and elevated CCL27/CCL28, consistent with selective Th recruitment." (PMID 41050670, 2025). "The role of CCR4, CCR8, CCR10, and CCR6 or their ligands has been proposed in atopic dermatitis (AD), psoriasis, cutaneous lupus erythematosus, systemic sclerosis, or malignant skin tumors, but not in CU." (PMID 37371632, 2023). "In human skin, patients with psoriasis expressed a higher level of CCL27, a ligand of CCR10, compared to healthy controls, indicating that the CCR10/CCL27 signal facilitates the development of psoriasis." (PMID 34831296, 2021). "In contrast, the lack of CCR6 and CCR10 expression suggests a less skin inflammatory profile of CU than AD and psoriasis, where both receptors are well-described for their role." (PMID 37371632, 2023). "However, in mouse models of inflammation, a decrease in the number of CCR10+ ILC in the skin has been reported, in addition to a decreased expression of CCL27 in psoriasis." (PMID 28303135, 2017).
breast carcinoma (8 papers, 2018 to 2025). "To date, it has been reported that the expression of CXCR4, CCR7, and CCR10 was associated with breast cancer metastases." (PMID 33244467, 2020). "In breast cancer CCR10 correlates with stage, capsular invasion, and nodal metastasis, with CCL27 inducing MMP-7 and ERK1/2 activation, CCR10 inhibition suppresses both." (PMID 41050670, 2025). "The screening results showed that none of the receptors for Cx3cl1 (CX3CR1), Cxcl16 (CXCR6), Ccl17 (CCR4, DARC, CCR10) or IL6 (IL6R) was more expressed in basal B compared to basal A or luminal breast cancer cells." (PMID 38055067, 2023). "MKL1 expression was positively correlated with C-C motif chemokine receptor 10 and C-X-C motif chemokine receptor 3 in breast cancer." (PMID 34761735, 2022). "CCR10 expression was discovered to be elevated in breast cancer cells, and the CCL27/CCR10 axis eventually promoted breast cancer cell invasion and migration via elevating MMP-7." (PMID 36250005, 2022).